C1GALT1C1 (C1GALT1 specific chaperone 1)
Description:
Probable chaperone required for the generation of 1 O-glycan Gal-beta1-3GalNAc-alpha1-Ser/Thr (T antigen), which is a precursor for many extended O-glycans in glycoproteins. Probably acts as a specific molecular chaperone assisting the folding/stability of core 1 beta-3-galactosyltransferase (C1GALT1).
Synonyms: C38H2-L1; C1GalT2; COSMC; HSPC067; AHUS8; MST143; TNPS
Tractability: Antibody: UniProt predicts a signal peptide or a membrane-spanning region. PROTAC: ubiquitination databases record sites on it; its protein half-life has been measured.
Gene: Protein-coding gene on chromosome X (120,625,674 to 120,630,054, reverse strand). Ensembl gene ENSG00000171155.
Subcellular location: Membrane
Subcellular location (Human Protein Atlas): Vesicles
Pathways (Reactome):
Disease: Defective C1GALT1C1 causes TNPS
Metabolism of proteins: O-linked glycosylation of mucins
Gene Ontology:
Molecular function: glycoprotein-N-acetylgalactosamine 3-beta-galactosyltransferase activity; protein binding
Biological process: protein O-linked glycosylation
Cellular component: extracellular exosome; Golgi membrane; membrane
Gene-disease validity (ClinGen):
ClinGen rates the evidence that C1GALT1C1 causes each of these diseases.
hemolytic uremic syndrome, atypical, 8, with rhizomelic short stature (X-linked): Limited.
Homologues: Orthologues: chimpanzee C1GALT1C1 (100% identical), macaque C1GALT1C1 (99% identical), dog C1GALT1C1 (95% identical), rabbit C1GALT1C1 (94% identical), guinea pig C1GALT1C1 (93% identical), mouse C1galt1c1 (93% identical), rat C1galt1c1 (93% identical), tropical clawed frog c1galt1c1 (67% identical), zebrafish c1galt1c1 (53% identical), Drosophila melanogaster tgy (23% identical), Drosophila melanogaster CG18558 (23% identical), Drosophila melanogaster CG2983 (23% identical), and 8 more. Paralogues in human: C1GALT1C1L (64% identical), C1GALT1 (28% identical).
Diseases named in the same sentence as C1GALT1C1 in open-access papers:
C1GALT1C1 is named in the same sentence as 25 diseases in open-access papers, as found by Europe PMC text mining. Sharing a sentence is not in itself a finding about the gene and the disease. The quoted sentences say what the papers report.
colon cancer (6 papers, 2012 to 2024). "Overexpression of C1GALT1C1 in human colon cancer cells significantly enhances cell migration and invasion, with activation of the EMT signature as the underlying mechanism." (PMID 38396140, 2024). "By contrast, knocking down C1GalT1C1 decreases malignant behaviours and the signalling pathways, suggesting that the chaperone can promote malignant phenotypes of colon cancer cells, mainly via activation of the MEK/ERK and PI3K/Akt signalling pathways." (PMID 30038662, 2018). "In the case of C1GalT1C1, forced expression of the chaperone in colon cancer cell lines increases T antigen expression and enhances cell growth, migration, and invasion, and this phenotype is associated with the increased phosphorylation of ERK and AKT." (PMID 30038662, 2018).
breast carcinoma (5 papers, 2015 to 2024). "We investigated the influence of truncated O‐glycan trees, also referred to as Tn antigen, following the inactivation of C1GALT1‐specific chaperone 1 (COSMC) on the general and MMP9‐specific proteolytic processing in MDA‐MB‐231 breast cancer cells." (PMID 39074261, 2024). "In this manner, MAN2A1 has been reported to be altered in glioblastoma, GALNT1 is altered in bladder cancer, C1GALT1C1 is altered in colorectal cancer, and UGT8 is altered in breast cancer." (PMID 30038662, 2018). "GALNT1 is increased in bladder cancer, C1GALT1C1 is increased in colorectal cancer and UGT8 is increased in breast cancer." (PMID 30038662, 2018).
colorectal cancer (5 papers, 2018 to 2024). A primary or metastatic malignant neoplasm that affects the colon or rectum. "Additionally, the targeted suppression of the C1galt1c1 gene using CRISPR/Cas9 technology results in increased levels of Tn antigen on the surface of the colorectal cancer cell line MC38 (MC38-Tnhigh)." (PMID 38699634, 2024).
COVID-19 (3 papers, 2022 to 2023). A disease caused by infection with severe acute respiratory syndrome coronavirus 2. "High levels of circulating GCNT4, RAB14, C1GALT1C1, CD207 and ABO have also been previously suggested to be causally associated with an increased risk of suffering from critical COVID-19, with comparable odds ratios varying from 1.12 to 1.35." (PMID 37958866, 2023).
IgA nephropathy (2 papers, 2009 to 2024). "Among inflammatory skin diseases, atopic dermatitis was found to increase the risk of IgA nephropathy, which may result from the decrease of GALNT12 and C1GALT1C1 expression and the increase of aberrant IgA1 production." (PMID 39119579, 2024). "Our results suggested that the mutation (including somatic mutation) of C1GALT1C1 gene did not significantly contribute to the genetic susceptibility or clinical manifestations of IgA nephropathy in Chinese population." (PMID 19778426, 2009).
atopic dermatitis (1 paper, 2024). "In the combined dataset, the expression of galactose-deficient IgA1-associated genes (including GALNT2, GALNT12, C1GALT1, C1GALT1C1 and ST6GALNAC2) were compared between atopic dermatitis patients and healthy controls." (PMID 39119579, 2024). "In the combined microarray dataset, the expression levels of GALNT12 and C1GALT1C1 in atopic dermatitis patients were significantly lower compared with controls (p = 2.3e−9; p = 0.00067), which may contribute to an increase in aberrant IgA1 synthesis." (PMID 39119579, 2024).
Hepatic fibrosis (1 paper, 2016). The presence of excessive fibrous connective tissue in the liver. "Another example is the significant upregulation of C1galt1c1 expression accompanied by an increase in T-antigen in the liver of mice with CCl4-induced hepatic fibrosis." (PMID 27281159, 2016).
Sepsis (1 paper, 2025). Sepsis is defined as life-threatening organ dysfunction caused by a dysregulated host response to infection. "Validation with an independent dataset confirmed the differential expression patterns of B3GNT5, C1GALT1C1, and GALNT14, reinforcing their potential as robust diagnostic biomarkers for sepsis." (PMID 39981259, 2025). "The expression trends of six Golgi-related genes (B3GNT5, FUT11, ST3GAL5, MAN1C1, C1GALT1C1, and GALNT14) aligned with the patterns observed in the hub genes from the initial sepsis dataset analysis." (PMID 39981259, 2025). "The key genes distinguishing sepsis from healthy conditions include B3GNT5, FUT11, ST3GAL5, MAN1C1, C1GALT1C1, and GALNT14." (PMID 39981259, 2025).
tumor (12 papers, 2013 to 2025). "Loss of C1GalT1C1 function eliminates T-synthase activity and the consequential Tn antigen expression in several human tumours." (PMID 30038662, 2018). "Conversely, the expression of C1GALT1C1 was notably reduced in the tumor compared to normal esophagus tissues." (PMID 38254730, 2024). "Tumor tissues exhibited a statistically significant upregulation in T-Synthase expression, while C1GALT1C1 expression was notably reduced, compared to normal esophagus tissues, probably causing T-Synthase to malfunction." (PMID 38254730, 2024). "We show that knockout of the C1galt1c1/Cosmc gene alters the cell-intrinsic properties of tumor cells, affecting genes involved in MAPK signaling, cell migration and angiogenesis and immune regulation." (PMID 33014816, 2020). "For example, the CH VAF in blood and tumor samples for the Core 1 Beta3-Galactosyltransferase-Specific Molecular Chaperone (C1GALT1C1) p.V276G variant, one of the eight potential immunosuppressive mutations in TII cells, varies from 7.1–23.5% for tumor and 4.1–21.6% for blood samples." (PMID 37573441, 2023).
cancer (9 papers, 2018 to 2025). A tumor composed of atypical neoplastic, often pleomorphic cells that invade other tissues. "C1GALT1C1, a molecular chaperone in the endoplasmic reticulum, has been linked to tumorigenesis in several cancers." (PMID 39981259, 2025). "Cosmc (C1GalT1C1) mutation could cause aberrant O-glycosylation and result in expression of Tn antigen on the surface of tumor cells (Tn+ cells), which is associated with the metastasis and prognosis of cancer progression." (PMID 37237420, 2023). "During carcinogenesis, C1GALT1C1 expression could be downregulated due to genetic mutations or, more interestingly, to an epigenetic modification: hypermethylation of the promoter leads to the silencing of C1GALT1C1 and to the accumulation of the cancer-associated Tn and STn antigens." (PMID 33804149, 2021). "Recent research has unveiled that knockout of the Zn2+-transporter SLC39A9 (ZIP9), alongside the well-described targets C1GALT1 (C1GalT1) and its molecular chaperone, C1GALT1C1 (COSMC), results in surface-expression of cancer-associated O-glycans." (PMID 38699634, 2024). "The analysis of mRNA expression for pivotal genes involved in the initial step of O-glycosylation reveals a substantial downregulation of C1GALT1C1 (COSMC) in the carcinomas." (PMID 38254730, 2024). "Analysis among the downregulated genes revealed a direct interaction within GALNT1, C1GALT1C1 and MUC1, a protein that carries the Tn antigen, which is present in most of the cancers, including uterine cervical cancer cells." (PMID 30038662, 2018).
infection (2 papers, 2023 to 2024). The state of being infected such as from the introduction of a foreign agent such as serum, vaccine, antigenic substance or organism. "AdV-5 replicated well in all O-glycosylation mutant cell lines on day 6 post-infection, though an initial delay in intracellular DNA synthesis was seen in C1GALT1C1 KO and GALNT1 KO on day 1 post-infection." (PMID 38757972, 2024). "This association slightly improved later in infection (20 hpi), but the capsid production did not intensify, suggesting HSV-1 infection is generally less robust in C1GALT1C1 KO." (PMID 37919266, 2023). "Interestingly, compared with WT, C1GALT1C1 KO- and GALNT3 KO-produced AdV-5 exhibited on average 11.4-fold and 6.5-fold lower titers, respectively, on day 6 post-infection, though not statistically significant." (PMID 38757972, 2024).
C1GALT1C1 also shares sentences with these, for which no sentence is quoted: pancreatic cancer (2 papers); pancreatic ductal adenocarcinoma (2); benign meningioma (1); bladder cancer (1); colorectal cancer 1 (1); familial hyperphosphatemic tumoral calcinosis (1); glioblastoma (1); hemangioma (1); infantile hemangioma (1); inflammatory skin disease (1); malignant meningiomas (1); meningioma (1); small cell lung carcinoma (1); vitiligo (1).